RPGR (retinitis pigmentosa GTPase regulator)
Diseases named in the same sentence as RPGR in open-access papers (continued):
Sharing a sentence is not in itself a finding about the gene and the disease.
myopia (continued). "Thus, we hypothesize that, like patients with RPGR mutation, patients with RPGRIP1 may be more prone to developing myopia." (PMID 38662103, 2024). "In addition to the novel mutations found in five known myopia genes (ADAMTS18, CSMD1, P3H2, RPGR, and SLC39A5), we also identified pathogenic variants in seven ocular disease genes (ABCA4, CEP290, HSPG2, PCDH15, SAG, SEMA4A, and USH2A) as novel candidate genes." (PMID 30245926, 2018). "Also, although myopia has been associated with xlRP caused by mutations in both RPGR and RP2, it is not exclusively found in this phenotype, and therefore was not used as a diagnostic criterion of xlRP." (PMID 26197217, 2015). "In view of this, in young patients with high myopia and ERG anomalies, CACNAF1, RPGR, and RP2 genotypes should be excluded even in the absence of night blindness." (PMID 39596324, 2024).
ciliopathy (15 papers, 2010 to 2024). A genetic disorder of the cellular cilia or the cilia anchoring structures, the basal bodies, or of ciliary function. "Ciliopathy-targeted gene therapy was also demonstrated in an XLRP model derived from patients with RPGR mutations." (PMID 38474133, 2024). "In RPGR-corrected patient iPSCs, the length was 2.653 μm, indicating that this ciliopathy was rescued by correction of the RPGR mutation." (PMID 29526738, 2018). "Mutations in the RPGR gene are the most common cause of RP, frequently associated with ciliopathies." (PMID 26124960, 2015). "We have specifically focused on two ciliary proteins – CEP290 and RPGR – that underlie photoreceptor degeneration and syndromic ciliopathies." (PMID 23351659, 2012). "Why then is only CEP290 associated with other syndromic ciliopathies even though RPGR is ubiquitously expressed?" (PMID 23351659, 2012). "CRISPR-Cas9-mediated correction of RPGR mutation rescued photoreceptor structure and electrophysiological property, reversed the observed ciliopathy, and restored gene expression to a level in accordance with that in the control using transcriptome-based analysis." (PMID 29526738, 2018). "In addition, recent studies have shown that the USH interactome is molecularly linked to other proteins whose mutations lead to ciliopathies, including RPGR and CEP290." (PMID 26881841, 2016). "Given a frequent occurrence of RPGR mutations in severe photoreceptor degeneration due to ciliary disorders, our results provide insights into pathways resulting in altered mature cilia function in ciliopathies." (PMID 26068394, 2015). "Taken together, the RPGR-interactome dissected in this study provides clues to further analyze the molecular mechanisms underlying the genetic and clinical heterogeneity associated with ciliopathies." (PMID 20664800, 2010). "Whilst suitable for a number of ciliopathy-related genes, such as RPGR (3.5 kb), many genes are beyond this capacity, including CEP290 (7.4 kb) and several of the Usher-syndrome-associated genes (MYO7A: 6.6 kb, CDH23: 10 kb, ADGRV1: 18.9 kb, USH2A: 15.6 kb)." (PMID 38474133, 2024). "We herein describe two patients with URP and possible ciliopathy, associated with two novel variants in AGBL5 and one novel variant in RPGR, respectively." (PMID 35892439, 2022). "RPGR variants lead also to atrophic macular degeneration (MIM: 300834) and ciliopathy (MIM: 300455)." (PMID 33712029, 2021). "Further investigation into Orai1, Septins and their relation with ciliopathy proteins, e.g. RPGR and its interacting proteins, will shed light on the underlying mechanisms of ciliopathies." (PMID 29796181, 2018). "Here, we focus on two ciliopathy genes involved in retinal dystrophy: CEP290, mutations in which cause up to 15 to 25% of LCA; and RPGR, the most common cause of X-linked RP and one of the most frequent causes of all forms of RP." (PMID 23351659, 2012). "Mutations in the RPGR gene and its interacting partners, RPGRIP1 and RPGRIP1L, cause ciliopathies, but the function of their proteins remains unclear." (PMID 29796181, 2018). "In this review we have discussed differences between human ciliopathies and their respective mouse models, focusing on CEP290, RPGR and their interactors." (PMID 23351659, 2012). "We provide compelling evidence that RPGR, RPGRIP1 and RPGRIP1L may function in ciliopathy by regulating the activity of proteasome and mediating SOCE." (PMID 29796181, 2018). "Our results demonstrate that the RPGR protein complex is required for regulating proteasomal activity and for modulating SOCE, which may contribute to the ciliopathy phenotype." (PMID 29796181, 2018).
choroideremia (11 papers, 2019 to 2025). Choroideremia (CHM) is an X-linked chorioretinal dystrophy characterized by progressive degeneration of the choroid, retinal pigment epithelium (RPE) and retina. "Dr. Kanmin Xue discussed clinical studies using subretinal injections of an AAV2 vector expressing REP1 to treat choroideremia and of an AAV8 vector expressing codon-optimized retinitis pigmentosa GTPase regulator gene (RPGR) to treat X-linked retinitis pigmentosa." (PMID 34003982, 2021).
cone dystrophy (11 papers, 2007 to 2023). An inherited ocular disorder characterized by the loss of cone cells, the photoreceptors responsible for both central and color vision. "At the molecular level, this uncovers for the first time one of the pathogenic mechanisms of the cone dystrophy phenotype associated with distal RPGR variants which disrupt the integrity of the basic domain." (PMID 36445968, 2022). "RPGR is the major causative gene for X-linked RPs, but it also accounts for some X-linked CRD with its locus referred as COD1 or CORDX1 and cone dystrophies." (PMID 17270046, 2007). "Considering that the majority of cone dystrophies are associated with pathogenic RPGR variants at the distal end of the ORF15, we hypothesized that the distal part of the protein plays an important role in normal functioning of cone photoreceptors." (PMID 36445968, 2022). "The RPGR gene has been associated with several disease patterns, including rod–cone dystrophy (RCD, 70%), cone–rod dystrophy (CORD) (6–23%), and cone dystrophy (COD) (7%)." (PMID 37895299, 2023). "Here we also show that truncating RPGRORF15 variants, which affect only parts of the basic domain, also significantly impair the RPGR glutamylation and lead to the cone dystrophy phenotype." (PMID 36445968, 2022). "Ectopic nuclei are a hallmark of certain cone dystrophies, as shown in the XLPRA dogs bearing mutations in the RPGR photoreceptor ciliary protein as well as in the model of slow progressive retinopathy in Shetland sheepdogs." (PMID 23977029, 2013). "This has implications for ongoing gene therapy clinical trials where the application of RPGR with impaired glutamylation may be less effective in treating RGPR dystrophies and may even convert a rod–cone dystrophy into a cone dystrophy phenotype." (PMID 36445968, 2022).
Blindness (10 papers, 2011 to 2026). Blindness is the condition of lacking visual perception defined as a profound reduction in visual perception. "Mutations in retinitis pigmentosa GTPase regulator (RPGR) cause photoreceptor degeneration, vision loss, and eventual blindness." (PMID 41941273, 2026). "Legal blindness was reached at an earlier age in patients with RPGR mutations (median 45 years) than in patients with USH2A mutations (median 58 years) or RHO mutations (median 77 years)." (PMID 32571342, 2020). "Mutations in the ciliary protein RPGR (retinitis pigmentosa GTPase regulator) are a prominent cause of severe blindness disorders due to degeneration of mature photoreceptors." (PMID 26068394, 2015). "Longitudinal studies assessing the natural history of X-linked RP due to RPGR mutations, also summarised in a recent systematic review, reported rapid progression rates with severe visual impairment and blindness by age 40–50, with few measurable metrics, including BCVA." (PMID 36498452, 2022). "Male subjects carrying the RPGR gene variant usually suffered from night blindness early in life, with rapid and severe progressive loss of peripheral vision, followed by progressive loss of central vision in the second to fourth decades life, which could progress to legal blindness." (PMID 38343445, 2023).
Leber congenital amaurosis (10 papers, 2012 to 2025). Leber congenital amaurosis (LCA) is a retinal dystrophy defined by blindness and responses to electrophysiological stimulation (Ganzfeld electroretinogram (ERG)) below threshold, associated with severe visual impairment within the first year of life. "These genes are known to cause: X-linked RP (RPGR), autosomal recessive RP (MAK and EYS), autosomal dominant RP (PRPF31), Stargardt disease (ABCA4), and Leber congenital amaurosis (GUCY2D)." (PMID 32000842, 2020). "We now show that this shorter PRL transcript is also expressed in RPGR-XLPRA1 (X-Linked Progressive Retinal Atrophy 1, caused by a five-nucleotide deletion in the RPGR exon ORF15) and NPHP5-LCA (Leber Congenital Amaurosis, caused by a single nucleotide insertion in exon 10 of the IQCB1/NPHP5 gene)." (PMID 39294136, 2024).
Stargardt disease (8 papers, 2007 to 2024). "The unique characteristics of the photoreceptor mosaic in retinitis-pigmentosa-GTPase-regulator (RPGR)-associated retinopathy and Stargardt disease and the differentiation between them have been reported." (PMID 37763275, 2023). "For example, a previous study found images from Stargardt disease yielded a higher manual intergrader agreement than images from retinitis pigmentosa GTPase regulator (RPGR)-associated retinopathy." (PMID 32855844, 2020). "Mutations in RPGR and ABCA4 genes have previously been associated with XLRP and Stargardt Disease, respectively." (PMID 25544989, 2014).
night blindness (7 papers, 2020 to 2024). Inability to see clearly in dim light. "The eight RPGR variants in our cohort that resided between the 153rd and 780th RPGR amino acid residues resulted in RP and were associated with an early onset of nyctalopia and peripheral VF constriction." (PMID 36835250, 2023). "In this family, individual II:1, as an RPGR variant carrier, complained of night blindness since childhood and suffered from a sudden decline in vision in her 40s." (PMID 36276946, 2022). "In this family, III:3, an RPGR variant carrier, complained of night blindness since childhood, and her BCVA was 0.05 bilaterally." (PMID 36276946, 2022). "The patient was found to harbor the disease-causing RPGR variant c.1894_1897delGACA, p.Asp632Lysfs*4, which was segregated to both her mother and her daughter Her mother had a history of nyctalopia." (PMID 33712029, 2021). "There were two families (families 33 and 52) with a family history of RP and night blindness caused by the same mutation: RPGR c.2236_2237delGA." (PMID 33781268, 2021). "This was in clear contrast to those with RPGR and RP2 variants, with 81% who were myopic and suffered from more severe night blindness in the juvenile cohort." (PMID 39596324, 2024).
achromatopsia (6 papers, 2020 to 2024). Achromatopsia (ACHM) is a rare autosomal recessive retinal disorder characterized by color blindness, nystagmus, photophobia, and severely reduced visual acuity due to the absence or impairment of cone function. "Of 19 diseases, 10 had >10 participants: ABCA4 retinopathy; CNGB3- and CNGA3-associated achromatopsia; RPGR-associated disease; RPE65-associated disease; blue cone monochromacy (BCM); Bornholm eye disease (BED); TYR- and OCA2-associated oculocutaneous albinism; and GPR143-associated ocular albinism." (PMID 35704304, 2022).
macular degeneration (5 papers, 2007 to 2023). Loss of vision in the central portion of the retina (macula), secondary to retinal degeneration. "Although there have been no reports of lipid accumulation in the retinal pigment epithelium (RPE) in animal models or patients with RPGR mutations, macular degeneration has been observed in some RPGRORF15 patients, and altered RPE integrity has also been noted in rd9 mice." (PMID 37351277, 2023). "RPGRIP, RANBP2, NPM1, PDE6D, and NPHP5 were selected on the basis of protein interaction with RPGR or RPGRIP1 as these two proteins independently cause photoreceptor degeneration when mutated; ABCA4 was selected as a control gene, and because of its association with macular degeneration and RP." (PMID 17653054, 2007).
retinal ciliopathies (5 papers, 2018 to 2025). "This review will discuss the state of hiPSC-derived retinal organoid technology for accurately modelling prominent retinal ciliopathies related to genes, including RPGR, CEP290, MYO7A, and USH2A." (PMID 38474133, 2024). "Some examples are RPGR and BBS8, both causative of non-syndromic retinal ciliopathies when their mutations map in retina-specific exons exclusively present in photoreceptor isoforms." (PMID 36293380, 2022). "Together with our data showing abnormal actin cytoskeleton in hTERT-RPE1 cells and in the photoreceptors of RPGR KO mice, this suggests a role of the RPGR protein complex in regulating the actin cytoskeleton, which may underlie the pathogenesis involved in retinal ciliopathies." (PMID 29796181, 2018).
atrophic macular degeneration (4 papers, 2008 to 2023). Dry AMD is most common type of macular degeneration and affects 90% of the people who have the condition. "Mutations in RPGR (RP3, Xp21.1) are responsible for up to 70% of X-linked retinitis pigmentosa and also cause X-linked cone-rod dystrophy (CORDX1) and atrophic macular degeneration." (PMID 19096719, 2008).
macular dystrophies (4 papers, 2021 to 2024). "Although all our patients were diagnosed clinically with STGD, the overlapping of phenotypes between different macular dystrophies and several stages of ABCA4-associated retinopathy could result in a misdiagnosis of STGD with mutations in phenocopying genes, such as PRPH2, ROM1, CRX, or RPGR." (PMID 33841504, 2021).
primary ciliary dyskinesia (4 papers, 2008 to 2026). A rare, genetically heterogeneous, primarily respiratory disorder characterized by chronic upper and lower respiratory tract disease. "Primary ciliary dyskinesia has been associated with X-linked retinitis pigmentosa in patients carrying RPGR mutations." (PMID 37555648, 2023). "In addition to the phenotype of RP, mutations in exons 6, 8, and 10 of RPGR have been associated with features of primary ciliary dyskinesia, hearing dysfunction, sinusitis, and recurrent infections." (PMID 18552978, 2008).
Duchenne muscular dystrophy (3 papers, 2017 to 2025). Duchenne muscular dystrophy (DMD) is a neuromuscular disease characterized by rapidly progressive muscle weakness and wasting due to degeneration of skeletal, smooth and cardiac muscle. "When XK gene segment deletions are excessive, they may involve contiguous XK genes, such as the CYBB and RPGR genes, which could result in “Xp21 DNA microdeletion syndrome”, including XLRP, chronic granulomatous disease, Duchenne muscular dystrophy, and ornithine transcarbamylase deficiency (OTC)." (PMID 38343445, 2023). "Larger telomeric deletions can also involve the retinitis pigmentosa GTPase regulator (RPGR) gene, responsible for X-linked retinitis pigmentosa, and DMD, causing Duchenne muscular dystrophy." (PMID 29430280, 2017).
Usher syndrome (3 papers, 2017 to 2024). A syndromic diseae characterized by the association of sensorineural deafness (usually congenital) with retinitis pigmentosa and progressive vision loss. "Moreover, the C-terminus of RPGR interacts with whirlin, mutations of which result in Usher syndrome, and nucleophosmin, which functions in cell division." (PMID 34800980, 2021). "Support for a role of RPGR and gelsolin in ciliary function and rhodopsin trafficking comes from work examining Usher Syndrome, a syndromic form of RP and deafness." (PMID 28814713, 2017).
X-linked rod-cone dystrophy (3 papers, 2021 to 2025). "For X-linked rod-cone dystrophy, ROs have been employed to model RPGR mutations causing abnormal splicing." (PMID 39422807, 2025). "Variants in RPGR are the main contributor to X-linked rod-cone dystrophy (RCD), and RPGR gene therapy approaches are in clinical trials." (PMID 35330501, 2022).
cervical carcinoma (2 papers, 2020 to 2023). A carcinoma arising from either the exocervical squamous epithelium or the endocervical glandular epithelium. "Two genes, TEKT2 and RPGR, were associated with lymph node metastasis and prognosis in cervical cancer, and were used to construct a lymph node metastasis-related predictive signature." (PMID 37427104, 2023). "TEKT2 and RPGR have been found to be associated with lymph node metastasis in cervical cancer." (PMID 37427104, 2023). "To clarify the role of TEKT2 and RPGR in cervical cancer, we investigated TEKT2 and RPGR expression in seven cervical cancer tissues and three normal cervical tissues." (PMID 37427104, 2023). "The expression of TEKT2 and RPGR was significantly downregulated in cervical cancer tissues, especially in metastatic lymph node tissues." (PMID 37427104, 2023). "The expression of TEKT2 and RPGR was significantly downregulated in cervical cancer tissues, especially in lymph node metastatic tissues." (PMID 37427104, 2023). "Analysis of the Human Protein Atlas data revealed that TEKT2 and RPGR protein levels were also downregulated in cervical cancer samples." (PMID 37427104, 2023). "Furthermore, the sensitivity of patients to chemotherapy drugs was estimated based on the predictive signature and the expression of TEKT2 and RPGR was investigated in the cervical cancer tissue samples." (PMID 37427104, 2023). "However, the role of RPGR in cervical cancer remains unclear and requires further investigation." (PMID 37427104, 2023).
Leber hereditary optic neuropathy (2 papers, 2020 to 2024). Leber's hereditary optic neuropathy (LHON) is a mitochondrial neurodegenerative disease affecting the optic nerve and often characterized by sudden vision loss in young adult carriers. "In the pediatric cohort, 78.8% of families showed causative variants in autosomal genes (most frequently ABCA4 and BEST1), 20.7% in X-linked genes (most commonly RS1 and RPGR), and 0.5% in mitochondrial genes (associated with Leber hereditary optic neuropathy)." (PMID 32423767, 2020).
nephronophthisis (2 papers, 2010 to 2022). Progressive tubulointerstitial injury, inherited in an autosomal recessive pattern, caused by mutations in genes involved in ciliary function, which may result in an end stage renal failure. "We found that RPGR associates with a ciliary protein nephrocystin-4 (nephroretinin; NPHP4) that is mutated in nephronophthisis (NPH) and RP (Senior-Løken syndrome)." (PMID 20664800, 2010).
retinitis pigmentosa 3 (2 papers, 2023 to 2024). Any retinitis pigmentosa in which the cause of the disease is a mutation in the RPGR gene. "The RPGR was discovered in a patient with XLRP, retinitis pigmentosa-3 (RP3) and could, in a first attempt, be assigned to a genomic segment of less than 1000 kb on the short arm of the human X chromosome (Xp21.1-p11.4,)." (PMID 37107692, 2023).
albinism (1 paper, 2022). A congenital disorder characterized by partial or complete absence of melanin pigment in the eyes, hair, or skin. "Significantly increased odds of a longer AL (≥26 mm) were observed for BCM and BED and also (but to a lesser extent) for TYR- and OCA2-associated albinism, as well as for RPE65- and RPGR-associated disease." (PMID 35704304, 2022).
Atrophy (1 paper, 2025). Any weakening or degeneration, especially through lack of use. "The genotype-phenotype correlation analysis revealed that 30 of 41 patients with RPGR mutations also exhibited RPE atrophy, suggesting that RPGR defects may directly compromise RPE structure and function, which is a plausible contributor to retinal dysfunction in these patients." (PMID 41288322, 2025).